IL1B (interleukin 1 beta)
Diseases named in the same sentence as IL1B in open-access papers (continued):
Sharing a sentence is not in itself a finding about the gene and the disease.
tumor (continued). "This is probably due to the low levels of both membrane and soluble TRAIL basally expressed by pIL6-TRAIL+-GFP+-UC-MSCs, since the transcription of TRAIL is reinforced by both IL-1α and IL-1β usually abundant within the tumor sites." (PMID 28962646, 2017). "The pro-inflammatory cytokines; IL-1β, IL-6, TNF-α and GM-CSF have been implicated in cell biology changes required for tumour progression." (PMID 28427184, 2017). "In our dataset evidence of inflammation comes from the increased levels of THBS2 and SPARC in the tumor stroma that are both induced by IL1β in fibroblasts in vitro." (PMID 29176937, 2017). "Cytokines, like TNF, IL-1β, IL-4, IL-13, and TGF-β, secreted by medullary cells, can also lead to the mutation of cancer related genes, and thus, the promotion of tumor formation." (PMID 29212288, 2017). "Because when the tumor occurs, the NLRP3 inflammasome was activated and produced IL-1β to form an inflammatory microenvironment and promoted tumor progression, and the progressive tumors would further stimulate NLRP3 inflammasome to produce more IL-1β." (PMID 28865486, 2017). "Together suggest that IL-1β secreted by IRISOE TNBC tumor cells induces expression of its own receptor IL-1R on the surface of the negative naïve MSCs." (PMID 29262555, 2017). "M1 macrophages have tumor-killing capacity and express a number of factors including iNOS, IL-1β, and TNF-α." (PMID 28415741, 2017). "In a tumor microenvironment, γδT cells in the lungs can also be activated and secrete IL-17, in a γδTCR-independent and IL-1β- and IL-23-dependent manner." (PMID 28912779, 2017). "Some studies indicated that IL-1β can trigger the activation of both Akt pathway and NF-κB pathway, which appears to be important molecular links between inflammation and tumor." (PMID 28035062, 2017). "Overall, our data demonstrate that treatment of DEX reduces expression of pro-inflammatory cytokines, especially IL-1β and IL-18, and thus enhances immunosurveillance in the tumor microenvironment and anti-metastatic actions." (PMID 28591224, 2017). "As age-dependent increased IL1-β levels in the present study were reduced by tumor induction only in multiparous mice, we propose that long-term parity counteracts tumor spread by reducing angiogenesis and relieving immune suppression by the host tissue." (PMID 28966800, 2017). "We found deficiency of perforin significantly blocked the OT1 CTL-mediated rejection of EG7 tumours and also reduced IL-1β secretion." (PMID 28537251, 2017). "Following stimulation of endothelial cells with recombinant IL-1β, tumour cell adhesion to blood and lymphatic endothelial cell monolayers increased; however, a larger increase was observed in cells of lymphatic origin." (PMID 28551814, 2017). "The inhibition of inflammasomes or neutralization of their products, mainly IL-1β and IL-18, has profound inhibiting effects on carcinogenesis and tumor progression." (PMID 29312552, 2017). "Together suggest that IL-1β secreted by IRISOE tumor cells activates MSCs in a paracrine fashion to secrete CXCL1, which also in a paracrine fashion activates IRISOE tumor cells to secrete CCL2." (PMID 29262555, 2017). "IL-1α is found in tumour cell membranes and in intracellular locations, and is produced in larger amounts than IL-1β in highly metastatic tumours." (PMID 28381274, 2017). "Experiments with tumor-fibroblast co-cultures revealed that fibroblasts increase expression of TGF-β, TNF, and IL-1β cytokines in tumor cells, as well as stimulate TGF-β signaling." (PMID 28423685, 2017). "In any case, the interdependent effects of OPG and IL1B expressions further support the significance of OPG in inflammatory-driven tumor progression." (PMID 28143606, 2017). "IL-6, IL-1β, and LCN2, previously associated with tumor growth and metastasis, were up-regulated in LuM cells." (PMID 28410227, 2017).
tumor (continued). "IL-1β is produced primarily by activated macrophages and is involved in cell proliferation, differentiation, apoptosis, angiogenesis, and tumor invasion." (PMID 28337194, 2017). "Neutualization of these two inflammasomes released products, IL-1β and IL-18, has been suggested to be a promising therapeutic agent for tumor suppression in certain cancer types, indicating the importance of these two cytokines in the tumor microenvironment." (PMID 28591224, 2017). "Dexamethasone exerts its effects by diminishing cytokine production by tumours, increasing the expression level of tumour necrosis factor, and decreasing the expression levels of interleukin 1 beta and vascular endothelial growth factor." (PMID 27911278, 2017). "Overall, our data suggest that DEX, even at such a low dose, suppressed the expression of proinflammatory cytokines, namely IL-1β and IL-18, and the concordant decrease in MDSCs and TAMs in the tumor stroma." (PMID 28591224, 2017). "Together suggest that IL-1β secreted by IRISOE tumor cells activates in paracrine fashion MSCs to secrete CXCL1 that also in paracrine fashion activates IRISOE tumor cells to secrete VEGF." (PMID 29262555, 2017). "Further analysis showed that the level of IL-1β secreted by activated macrophages corresponded with the rate of tumour cell migration." (PMID 28551814, 2017). "To further confirm the anti-inflammatory effects of L-4F, we analyzed mRNA levels of the inflammatory cytokines IL-17A, IFN-γ, IL-6, and IL-1β in tumor tissues from Sc-4F- or L-4F-treated tumor-bearing mice." (PMID 29245934, 2017). "Chronic over activation of the IL-1β pathway has been considered as a tumor promoting condition, which is beneficial for IL-1β inhibition for tumor prevention or therapy." (PMID 28865486, 2017). "IL-1β stimulation of tumour cells significantly increased their migratory ability and a significant increase in migration was observed when MDA-MB-231 cells were stimulated with macrophage conditioned media (two of three donors)." (PMID 28551814, 2017). "KSHV-infected monocytes produce a general proinflammatory response similar to the KS tumor microenvironment cytokines with enrichment of IL-1α, IL-1β, and IL-6 compared to uninfected control cells." (PMID 29018115, 2017). "l-CDL 10 mg/kg or 20 mg/kg group significantly decreased the level of IL-1β in spinal cord and serum compared with the tumor group (p < 0.05, p < 0.01)." (PMID 28587280, 2017). "When both tumour cells and endothelial cells were simultaneously conditioned with IL-1β, adhesion was more markedly increased than when following stimulation of either cell type alone." (PMID 28551814, 2017). "Early release of TNF-α and IL-1β pro-inflammatory cytokines and efficient tumor Ags phagocytosis by monocytes take place and would probably create a favorable context for Ag processing and presentation." (PMID 29109725, 2017). "The aim is to inhibit the immune checkpoint, while either simultaneously suppressing the inflammatory responses (blocking IL-1b or IL-17), or inhibiting tumor cell proliferation with mitogen-activated protein kinase and EGFR inhibitors." (PMID 29312320, 2017). "We observed constitutively elevated levels of cytokines MCP-1, G-CSF, and RANTES in tumor cells, and of IL-1β, IL-8, MMP-1, MMP-2, and MMP-10 after co-culture." (PMID 28337194, 2017). "The expressions of CRF and IL-1β in the plasma and tumor tissues homogenate in model group mice was much higher than that in the control group mice (P < 0.01)." (PMID 28002791, 2017). "IL-1β is constitutively produced in astrocytomas and other brain tumors and can contribute to tumor growth and metastasis." (PMID 28346397, 2017). "As part of the tumour immunological microenvironment analysis, we determined the relative expression of pro-inflammatory (IL-1β, TNF-α, and IFN-γ), as well as regulatory (IL-10 and TGF-β) cytokines in tumour tissue." (PMID 28874690, 2017).
tumor (continued). "Together suggest that at least in culture, IL-1β secreted by IRISOE TNBC tumor cells recruits MSCs to the vicinity of tumor cells, most likely through inducing expression of IL-1R on naïve MSCs surface." (PMID 29262555, 2017). "Secretion of IL-1β was caspase-1 dependent, and treatment with caspase-1 inhibitor reduced IL-1β production by 73% and concomitantly reduced tumour cell adhesion to levels obtained with resting macrophages." (PMID 28551814, 2017). "Given that we observed a reduction in the levels of proinflammatory cytokines IL-6, IL-1β and TNFα within the tumour, we investigated changes in immune cell populations within the tumour and its microenvironment." (PMID 28416734, 2017). "In tumor-fibroblast co-cultures, fibroblasts increased expression of TGF-β, TNF, and IL-1β cytokines in tumor cells." (PMID 28423685, 2017). "In this study, RERG decreased IL8, IL6 and IL1β expression and angiogenesis in tumor xenografts in nude mice." (PMID 28659184, 2017). "It would be counterintuitive and deleterious for a tumor if TAMs produce IL-1β to mount an antitumor immunity." (PMID 28804221, 2017). "This work indicates that LMP1-mediated glycolysis regulates IL-1β, IL-6 and GM-CSF production through the NLRP3 inflammasome, COX-2 and P-p65 signaling pathways to enhance tumor-associated MDSC expansion, which leads to tumor immunosuppression in NPC." (PMID 28732079, 2017). "The expression of β-END and CRF in the plasma and tumor tissues of cinobufagin group were much higher than that of the model group mice, but the expression of IL-1β in the plasma and tumor tissues was much lower than that in the model group mice." (PMID 28002791, 2017). "The co-cultures of the tumor cells and monocytes were significantly enriched with the potent pro-inflammatory cytokines interleukin (IL)-1β and IL-8, known to support malignant progression." (PMID 28337194, 2017). "MET-induced IL-1β triggers pro-HGF secretion in tumor-associated astrocytes, establishing a pro-metastatic inflammatory tumor microenvironment." (PMID 28420162, 2017). "Early release of TNF-α and IL-1β pro-inflammatory cytokines and efficient tumor Ags phagocytosis by monocytes also occurs and would favor subsequent Ag processing and presentation." (PMID 29109725, 2017). "At a ∼250mm3 tumor volume, mice were divided into 4 groups intraperitoneally injected with: vehicle, Anakinra (human grade IL-1β antagonist; IL-1ra, 10mg/kg), SB265610 (CXCR2 inhibitor, 2mg/kg) or both (same concentrations) for 4 consecutive days." (PMID 29262555, 2017). "Caspase-1 cleaves and activates the proinflammatory cytokines IL-1β and IL-18 into their mature peptides, which contribute to the down-stream inflammatory response and formation of tumor microenviroment." (PMID 28424426, 2017). "It has been reported that the levels of TAM-derived tumor growth factor-β1 (TGF-β1), epidermal growth factor (EGF), chemokine [C-C motif] ligand 18 (CCL18), interleukin (IL)-18, IL-1β, and IL-8 are correlated with tumor progression." (PMID 28143526, 2017). "We therefore consider that intratumoural IL-1β and IL-33 is primarily responsible for IL-33 expression in P29 tumours." (PMID 26775708, 2016). "Then, we compared the ability of DRibbles made from different tumor cell lines to stimulate the IL-1β production from THP-1." (PMID 27490927, 2016). "Anakinra thus appeared to reduce neutrophil recruitment to the tumour, with tumour-derived IL-1β previously reported to recruit anti-cancer neutrophils to the tumour." (PMID 27100888, 2016). "IL-1β in the tumor microenvironment potentiates carcinogenesis by promoting local inflammatory responses and stimulating angiogenesis." (PMID 27487154, 2016). "Primary tumors from tumor-bearing mice, and normal mammary glands from naïve mice (controls) were collected, homogenized and assayed by IL-1β specific ELISA." (PMID 27786298, 2016).
tumor (continued). "On the basis of these observations, we concluded that autophagosomes released from many different tumor cells were potent inducers of IL-1β." (PMID 27490927, 2016). "Proinflammatory factors IL-6 and IL-1β are secreted by many cell types, such as immune cells and tumor, stromal, and endothelial cells, which play an important role in inflammation-associated carcinogenesis." (PMID 27057094, 2016). "Alternatively, in a murine colon carcinoma model, autophagy-dependent ATP release after MTX treatment promoted recruitment of IFNγ-producing CD8+ T cells into the tumor in an IL-1B-mediated fashion." (PMID 27933272, 2016). "Here, we demonstrate for the first time that NLRP3 and its inflammasome-associated proteins, ASC, IL-1β, and CASP1, are highly expressed in OSCC tumor tissues, as examined by immunohistochemistry (IHC), Western blot and RT-qPCR analyses." (PMID 27367024, 2016). "In summary, this study shows that the inflammasome and IL-1β pathway induces inflammatory microenvironments promoting tumor growth and metastasis." (PMID 27786298, 2016). "Chronic inflammation is one of the important factors of carcinogenesis, in which the inflammatory mediators such as TNFα, IL-1β and IL-6 secreted by macrophages promote tumour growth by deregulating the cell cycle checkpoints and cell repair machinery." (PMID 27270308, 2016). "To confirm that IL-1β production is the result of inflammasome activation in the tumor microenvironment, we examined the processing of pro-IL-1β proteins in tumor tissues by Western blot." (PMID 27786298, 2016). "IL-1β was abundant in P29 tumours at the mRNA level, particularly in the peripheral region, in B6 mice compared with those tumours in IL-33−/− mice, and IL-4, IL-6 and TRAIL expression was quite low in both types of tumours." (PMID 26775708, 2016). "IL-1β was released from tumor-associated macrophages to activate WNT signaling and to promote the growth of tumor cells." (PMID 27057094, 2016). "It was shown that the inflammatory tumorigenic microenvironment is derived from IL-1β secreted from the myeloid cells around the tumor, and the IL-1α secreted from the tumor cells accompanied with hypoxia, necrosis, or DNA damage." (PMID 28083070, 2016). "A large amount of molecules released by tumor cells or tumor-surrounding cells, including IL-1β, IL-4, IL-6, IL-10, IFN-γ and TGF-β, are reported to re-program immature myeloid cells to become immunosuppressive." (PMID 26967390, 2016). "Our microarray and qRT-PCR data suggested that metastatic tumor cells possess higher expression levels of endogenous IL-6 and IL-1β and their receptors." (PMID 27698389, 2016). "Lung tissues from naïve or tumor-bearing mice were homogenized and assayed for mature IL-1β protein production." (PMID 27786298, 2016). "We next investigated the tumor mRNA expression of some key cytokines, we observed significantly increased expression levels of IL-1β, and IL-6 in tumors from mice treated with LTD4 or PGE2 compared to vehicle treated mice." (PMID 27388564, 2016). "In vivo blockade of IL-1β using recombinant IL-1RA significantly decreased tumor development in the AOM/DSS mouse model of CAC, indicating a pro-tumorigenic role of IL-1β in this setting." (PMID 27148488, 2016). "It has been documented that IL-1β accumulated at the tumor site is involved in the MDSC generation in bone marrow and in their migration towards tumor lesions." (PMID 27827871, 2016). "RT-qPCR analysis of 20 paired tumor and adjacent normal tissue samples revealed that the mRNA levels of ASC, along with IL-1β, CASP1, and NLRP3 in ASC-associated NLRP3 inflammasome were significantly elevated in OSCC tissues." (PMID 27367024, 2016). "We cannot be sure to what extent the observed anti-tumour effects are due to reduced IL-1B signalling." (PMID 27765923, 2016). "IL-1β can act on intestinal epithelial cells (IECs) and directly on tumor cells to induce their proliferation." (PMID 27148488, 2016).
tumor (continued). "Piezo2 knockdown decreased VEGF- or IL-1β-mediated pathological angiogenesis, implying that Piezo2 plays an anti-angiogenic role during tumor growth." (PMID 27329839, 2016). "Because we knew the importance of IL-1β to tumor progression and metastasis, we decided to study the effect of this cytokine along with tumor products on dendritic cell differentiation." (PMID 27088097, 2016). "IL-1β, a pleiotropic cytokine, is important for inflammation, immunity, hematopoiesis, and has tumor-promoting effects." (PMID 27487154, 2016). "In a recent study by our group using a mouse model of chemically induced colon carcinogenesis, we showed that tumor-bearing animals treated with jacalin produced increased levels of proinflammatory cytokines such as IL-1β, TNF, IL-12, and IFN-γ." (PMID 27119077, 2016). "Together with TNF-α, IL-1β also increases NF-κB transcription thus increasing tumor adhesiveness, invasion and angiogenesis." (PMID 26896068, 2016). "We found that the amount of mature or processed IL-1β and caspase-1 proteins in tumor tissues of caspase-1 KO and NLRP3 KO mice were significantly decreased, compared to that of WT mice." (PMID 27786298, 2016). "A recent study showed that the impaired anticancer ability of MG1655 (LPS-competent E.coli), which displayed similar tumor targeting capacity as S. enterica, is due to reduced IL-1β expression." (PMID 27835896, 2016). "Similar results were obtained for E0771 tumours where we observed a significant increase in the expression of Il1b." (PMID 27708283, 2016). "The effect of IL-1β shRNAs on tumor growth in vivo was evaluated using cancer xenograft volume changes." (PMID 26831400, 2016). "Since inflammation plays an important role in tumor development, which mainly acts through the medium of a number of inflammatory cytokines, such as IL‐1β and TNF‐α." (PMID 27734611, 2016). "Paracrine signals from IL-1β activate gene expression pathways in neighboring cells and vice versa, ultimately setting up a cycle of reinforcement and generating a tumor favorable microenvironment for oral carcinogenesis." (PMID 26831400, 2016). "Our results indicate that the activation of inflammasomes and production of IL-1β in vivo provide inflammatory microenvironments to promote tumor growth and metastasis." (PMID 27786298, 2016). "IL-1β expression has been reported in various cancers and increased local IL-1β levels usually correlate with tumor invasiveness and poor patient prognosis." (PMID 27487154, 2016). "Inflammasome-mediated IL-1β can induce the recruitment of TAMs and MDSCs which promote tumor development as reported in this paper." (PMID 27786298, 2016). "CD11b cells from tumor tissues of WT mice produced a considerable amount of IL-1β, but spleen CD11b cells produced a relatively low concentration of IL-1β." (PMID 27786298, 2016). "Stimuli resulting from tumor products or from IL-1β produced different results regarding the appearance of macrophage markers in these cells, with leukemic cell products increasing CD68 and CD16 expression, a feature not observed with IL-1β." (PMID 27088097, 2016). "After ingenol mebutate treatment in vivo (i) B16 tumour tissue show a ≈1.5 fold induction of IL-1β mRNA and (ii) tumour treatment sites show a ≈2.5 fold increase in IL-1β protein levels." (PMID 27100888, 2016). "In our study, administration of anakinra significantly reduced expression of TNF alpha and IL-1B in bone and reduced levels of these molecules is likely to have contributed to the anti-tumour effects observed." (PMID 27765923, 2016). "Chemokines and cytokines are extensively produced in the tumor microenvironment regardless of the initial triggers and mediators such as IL-1b, TNFa and IL-6 directly promoted the tumor progression in experimental models of colorectal cancer." (PMID 26859579, 2016).